PRMT5 (protein arginine methyltransferase 5)
Diseases named in the same sentence as PRMT5 in open-access papers (continued):
Sharing a sentence is not in itself a finding about the gene and the disease.
melanoma (continued). "The cytoplasmic predominance of PRMT5 suggests that its role is not exclusive to control of gene expression in melanoma." (PMID 24098663, 2013). "Due to the heterogeneous genotypic profile in human melanoma, there was no clear relationship between BRAF or NRAS that predicted effects of PRMT5 loss on proliferation." (PMID 24098663, 2013). "In light of the fact that BRAF status in melanoma is a predictor of response to BRAF inhibitors, it would also be important to examine the expression and localization of PRMT5 in BRAF inhibitor-resistant versus inhibitor-sensitive cells, or in tumors which are or are not responsive to immunotherapy." (PMID 24098663, 2013). "However, the full effects of inhibition of CDK4/6 on splicing events in melanoma and the extent to which they are dependent on PRMT5 has not been established." (PMID 37917641, 2023). "Interestingly, PRMT5 depletion antagonizes melanoma growth in immunocompetent, but not immunocompromised, mice." (PMID 35111150, 2021). "Melanoma cell lines were transfected with PRMT5 siRNA or scrambled negative control sequence." (PMID 24098663, 2013). "However, no publications to date have explored PRMT5 or its relationship with MITF and cell cycle regulatory proteins in primary melanoma specimens." (PMID 24098663, 2013).
hepatocellular carcinoma (42 papers, 2015 to 2025). A malignant tumor that arises from hepatocytes. "In hepatocellular carcinoma, PRMT5 has been linked to the increased half-life of SREBF1, an inducer of lipogenesis in the liver, which did not appear in the network analysis." (PMID 38132437, 2023). "For example, LINC01138 specifically binds with PRMT5 in hepatocellular carcinoma cells, and this association may be a potential therapeutic target in hepatocellular carcinoma." (PMID 31186036, 2019). "PRMT5 is overexpressed in hepatocellular carcinoma (HCC), and associated with aggressive clinicopathological parameters, such as poor differentiation, higher incidence of hepatic vein invasion, larger tumor size, higher AFP levels and worse prognosis." (PMID 34513846, 2021). "MP is known to have a tumor suppressor role by dephosphorylating the activating phospho-Thr80 site of PRMT5, a mechanism previously demonstrated in hepatocellular carcinoma cells." (PMID 41301499, 2025). "A recent study also reports that SMYD4 is upregulated in hepatocellular carcinoma, forming a positive feedback loop with the arginine methyltransferase PRMT5." (PMID 38892284, 2024). "Our analysis of the data has unveiled a notable pattern of PRMT5 overexpression, specifically in hepatocellular carcinoma (HCC)." (PMID 38666828, 2024). "Huang’s group showed that competitive inhibition of the interaction between CDK4 and CDKN2A by PRMT5 is essential for glucose-induced hepatocellular carcinoma cell proliferation." (PMID 39255317, 2024). "A study showed that LINC01138 by interacting with PRMT5 to facilitate tumor progression in hepatocellular carcinoma." (PMID 36366731, 2023). "A recent study reported that PRMT5 negatively regulated MHC-II expression in MYC-driven hepatocellular carcinoma." (PMID 35493527, 2022). "PRMT5 silencing in MYC-overexpressing hepatocellular carcinoma cells directly regulated MHC-II expression by decreasing the in vitro H3R8me2s and H4R3me2s enrichment on CIITA and CD74 promoters." (PMID 35493527, 2022). "It was recently proved that the phosphorylation of PRMT5 on T80 residue increases its methyltransferase activity; furthermore, elevated levels of the enzyme were measured in the case of human hepatocellular carcinoma and other types of tumours." (PMID 36232624, 2022). "For example, in the case of hepatocellular carcinoma, the phosphorylation/dephosphorylation of PRMT5 on T80 modulates its methyltransferase activity, and the dephosphorylating myosine phosphatase has a tumour suppressor role." (PMID 36232624, 2022). "In a previous study on hepatocellular cancer, there was a significant downregulation of β-catenin upon PRMT5 silencing." (PMID 34200178, 2021). "In hepatocellular carcinoma, PRMT5-catalyzed repressive dimethylation on H4R3 at the B-cell translocation gene 2 (BTG2) promoter increases cell proliferation through the ERK signaling pathway." (PMID 34685445, 2021). "Hepatocellular carcinoma (HCC) is an example of a cancer type that often displays elevated PRMT5 and SND1 levels, and there is evidence that hyperactivation of this axis is oncogenic." (PMID 33768972, 2021). "PRMT5 inhibits the expression of BTG2 in hepatocellular carcinoma through the ERK signaling pathway, thereby promoting cell proliferation." (PMID 34476262, 2021). "LINC01138 regulates the expression of downstream genes through modulating protein arginine methyltransferase 5 (PRMT5), promoting hepatocellular carcinoma (HCC) cell proliferation, tumorigenicity, tumor invasion, and metastasis in vitro and in vivo." (PMID 34745388, 2021). "LINC01138 induces malignancies via activating arginine methyltransferase 5 and interacting with PRMT5 to promote SREBP1-mediated lipid desaturation individually in hepatocellular carcinoma and clear cell renal cell carcinoma." (PMID 31433789, 2019).
hepatocellular carcinoma (continued). "Recently, Li et. al. found LINC01138 can stabilize PRMT5 through physical interactions in hepatocellular carcinoma and facilitate the proliferation, invasion and metastasis of cancer cells." (PMID 30546056, 2018). "We identified the protein arginine methyltransferase 5 (PRMT5) enzyme of the methylosome complex as a MYPT1-binding protein uncovering the nuclear MYPT1-interactome of hepatocellular carcinoma cells." (PMID 28074910, 2017). "Here, we report that upon glucose induction, protein arginine methyltransferase 5 (PRMT5) exerts a profound effect on the G1-S cell cycle progression via directly interacting with cyclin dependent kinase 4 (CDK4) in hepatocellular carcinoma (HCC)." (PMID 27708221, 2016). "Additionally, we utilized in-house generated NGS data to explore PRMT5 expression in dysplastic nodules compared to hepatocellular carcinoma." (PMID 38666828, 2024). "Our findings align with previous studies in hepatocellular carcinoma, where MYPT1 was shown to act as a tumor suppressor by regulating PRMT5 activity." (PMID 41301499, 2025). "Competitive binding between HNRNPH1 and SRSF3 to PRMT5 pre-mRNA promotes PRMT5-ISO5 production and increases radiosensitivity in hepatocellular carcinoma cells." (PMID 38405130, 2024). "In hepatocellular carcinoma, DW14800, a novel inhibitor of protein arginine methyltransferase 5 (PRMT5), promotes the differentiation of CSCs by downregulating the expression of HNF4α and enhancing methylation of H4R3me2s." (PMID 35488254, 2022). "In hepatocellular carcinoma (HCC), upregulation of PRMT5 correlated with a worse prognosis, and PRMT5 could regulate the proliferation of HCC cells in vitro." (PMID 30922330, 2019). "IGF2BP3 could promote the interaction between LINC01138 and PRMT5 by combining with LINC01138 and ultimately increase PRMT5 stability in hepatocellular carcinoma." (PMID 35676262, 2022). "Protein arginine methyltransferase 5 (PRMT5), a type II PRMT, is highly expressed in some tumors, but its role in hepatocellular carcinoma (HCC) is still unknown." (PMID 26541651, 2015). "As expected, we validated that HBV could reduce the methylase activity of PRMT5, but not the levels of PRMT5 in hepatoma cells." (PMID 34373747, 2021). "However, the role of PRMT5 in hepatocellular carcinoma (HCC) progression remains unclear." (PMID 29441724, 2018). "Likewise, PRMT5-methylation of SREBP1, a transcription factor required for de novo lipogenesis, prevents its phosphorylation by GSK3β and subsequent ubiquitination by FBXW7, thereby increasing lipogenesis and tumor growth of hepatocellular carcinoma (HCC)." (PMID 32743345, 2020). "Moreover, in hepatocellular carcinoma (HCC), PRMT5 and β-catenin may competitively interact with metadherin (MTDH), an oncoprotein, which regulates the Wnt pathway to promote HCC metastasis." (PMID 32961708, 2020).
pancreatic cancer (37 papers, 2018 to 2026). "Increasing evidence suggest that PRMT5 is a promising therapeutic target for pancreatic cancer, and further research of its functions and underlying mechanisms is of great significance." (PMID 40384988, 2025). "In this study, we examined the roles of PRMT5 in pancreatic cancer and elucidated the underlying mechanism." (PMID 31851779, 2020). "Our study aimed to investigate the roles of PRMT5 in pancreatic cancer prognosis and progression and to explore the underlying molecular mechanism." (PMID 30922330, 2019). "Similarly, the PRMT5 gene has been implicated in the development of chemoresistance; conversely, its inhibition renders pancreatic cancer cells more susceptible to gemcitabine, a commonly used first‐ or second‐line chemotherapeutic agent." (PMID 40685330, 2025). "We further performed RNA‐sequencing on PRMT5‐knockdown pancreatic cancer cells, inhibited in vivo tumor growth, and revealed the positive regulation of cell death, positive apoptosis process, and enriched Hallmark of apoptosis after PRMT5 knockdown." (PMID 40384988, 2025). "Moreover, the same inhibitor also demonstrated that inhibition of PRMT5 significantly reduced gemcitabine resistance in pancreatic cancer caused by UBR7 depletion." (PMID 39703687, 2024). "Finally, an inhibitor that blocks PRMT5 (DS-437) significantly reduced gemcitabine resistance in pancreatic cancer caused by UBR7 depletion." (PMID 39424627, 2024). "In pancreatic cancer, PRMT5 is identified as a synthetic lethality target in combination with gemcitabine." (PMID 41513606, 2026). "By forming this positive PRMT5/c‐Myc feedback loop, PRMT5 fueled the proliferation of pancreatic cancer." (PMID 40384988, 2025). "In conclusion, PRMT5 forms a positive feedback loop with c‐Myc to promote the proliferation of pancreatic cancer." (PMID 40384988, 2025). "Taken together, by forming this positive feedback loop, PRMT5 functioned its oncogenic role and fueled the proliferation of pancreatic cancer." (PMID 40384988, 2025). "We then evaluated the expression of PRMT5 in nine pairs of pancreatic cancer and adjacent normal tissue, and the western blot detection exhibited higher PRMT5 in the pancreatic cancer." (PMID 40384988, 2025). "Combination of PRMT5 inhibition exhibited synergistically enhanced cytotoxicity of gemcitabine and palbociclib in pancreatic cancer." (PMID 40384988, 2025). "Recently, increasing studies have reported that high PRMT5 expression and its correlation with poor prognosis in multiple malignancies, including pancreatic cancer." (PMID 40384988, 2025). "Our group previously performed targeted in vivo CRISPR/Cas9 genetic screening, which led to the identification of the protein arginine methyltransferase 5 (PRMT5) as a possible therapeutic target against pancreatic cancer when combined with Gem." (PMID 40723820, 2025). "Alternatively, combining low concentrations of PRMT1 or PRMT5 inhibitors is well tolerated in mice and can synergically reduce growth and promote apoptosis in pancreatic cancer and DLBCL cancer cells." (PMID 40823091, 2025). "To reinforce the roles of c-Myc/PRMT5 as downstream effectors, we used c-Myc inhibitor or PRMT5 inhibitor for in vivo treatment in the pancreatic cancer liver metastasis model bearing TLR3 knockout cancer cells with NLS-TLR3 rescue." (PMID 40675966, 2025). "Given that the current first- or second-line treatment for patients with stage I–IV pancreatic cancer is Gem plus Ptx, we sought to assess the effect of a PRMT5 pharmacologic inhibitor in combination with Gem plus Ptx." (PMID 40723820, 2025). "PRMT5 inhibition exhibited synergistically enhanced cytotoxicity of other chemotherapeutic agents in pancreatic cancer." (PMID 40384988, 2025). "In turn, increased c‐Myc inhibited proteasome‐mediated degradation of PRMT5, maintaining its expression in pancreatic cancer." (PMID 40384988, 2025).
pancreatic cancer (continued). "Recent advancements in the development of protein arginine methyltransferases (PRMT) 5 (PRMT5) inhibitors (PRMT5is) represent a significant step forward and a potential therapeutic option for pancreatic cancer treatment." (PMID 40157258, 2025). "Combination of PRMT5 inhibition with gemcitabine resulted in conditional lethality and a synergistic reduction in pancreatic cancer growth." (PMID 40384988, 2025). "In summary, we postulated and validated the novel positive PRMT5/c‐Myc feedback loop via which PRMT5 exerted its pro‐proliferation role in pancreatic cancer." (PMID 40384988, 2025). "Clinically, we found the co-localization of TLR3, PRMT5 and c-Myc within the nuclei of cancer cells presented in tumor tissue sections obtained from pancreatic cancer patients undergoing neoadjuvant chemotherapy." (PMID 40675966, 2025). "In this study, we found PRMT5 promoted the proliferation, and both genetic and pharmacological inhibition of PRMT5 impeded pancreatic cancer tumorigenesis." (PMID 40384988, 2025). "The increased c‐Myc inhibited the proteasome‐mediated degradation of PRMT5, maintaining its expression in pancreatic cancer." (PMID 40384988, 2025). "PRMT5 regulates glycolysis in pancreatic cancer through the FBW7/cMyc axis and promotes the occurrence of pancreatic cancer tumors." (PMID 39424627, 2024). "Depletion of UBR7 increased PRMT5 protein stability, which in turn increased glycolysis in pancreatic cancer cells and Tregs." (PMID 39424627, 2024). "Mechanistically, depleted UBR7 increased the stability of PRMT5, thereby promoting glycolysis in pancreatic cancer cells." (PMID 39424627, 2024). "Taken together, these results indicate that UBR7 regulates the progression and GEM resistance of pancreatic cancer by regulating the expression of PRMT5." (PMID 39424627, 2024). "The epigenetic regulator protein arginine methyltransferase 5 (PRMT5) stabilizes c-Myc levels in pancreatic cancer cells by downregulating FBXW7, promoting tumor cell proliferation." (PMID 39749199, 2024). "Studies have also shown that PRMT5 promotes Warburg anaerobic glycolysis in human breast and pancreatic cancer cells, and PRMT5 knockdown also reduces glucose consumption or the extracellular acidification rate (ECAR)." (PMID 39424627, 2024). "Qin and colleagues showed that PRMT5 promoted glycolysis in pancreatic cancer through the F-box/WD repeat-containing protein 7 (FBW7)/cMyc axis." (PMID 37861293, 2023). "Patients with pancreatic cancer who display higher levels of PRMT5 expression present lower overall survival." (PMID 36902253, 2023). "Recent studies have shown that Protein arginine methyltransferase 5 (PRMT5) is overexpressed in pancreatic cancers, and these patients have a worse prognosis." (PMID 36765032, 2023). "In summary, targeting PRMT5 activity through T1-44 treatment results suppression of tumor growth in pancreatic tumor growth." (PMID 36765032, 2023). "A recent study reports the role of PRMT5 in glycolysis and tumorigenicity in pancreatic cancer, and PRMT5 promotes cancer cell migration and invasion." (PMID 33807786, 2021). "Combination of inhibitors of PRMT1 and PRMT5 has a synergistic cancer cell growth inhibition in pancreatic cancer and DLBCL cell lines and in pancreatic adenocarcinoma xenografts mouse models." (PMID 34522232, 2021). "We further showed that PRMT5 inhibition significantly decreases the survival of colorectal and pancreatic cancer cell lines." (PMID 34685445, 2021). "Curiously, the addition of PRMT1 to PRMT5 inhibition in a pancreatic cancer cell line induces a synergistic increase in >2400 novel ASEs compared with PRMT5 or PRMT1 inhibitor alone." (PMID 34680285, 2021). "For example, through the FBW7/CMYC axis, PRMT5 intensifies glycolysis and tumorigenicity of pancreatic cancer." (PMID 34476262, 2021). "Then, we examined the effect of PRMT5 on the invasive abilities of the pancreatic cancer cells performed with transwell invasion assay." (PMID 31851779, 2020).
pancreatic cancer (continued). "Our data showed that PRMT5 promoted cell proliferation, migration and invasion in pancreatic cancer cells, and promoted tumorigenesis." (PMID 31851779, 2020). "Taken together, our study demonstrates that PRMT5 plays oncogenic roles in the growth of pancreatic cancer cell and provides a potential candidate for pancreatic cancer treatment." (PMID 31851779, 2020). "In this study, we find that PRMT5 is up‐regulated in pancreatic cancer, and promotes proliferation, migration and invasion in pancreatic cancer cells, and promotes tumorigenesis." (PMID 31851779, 2020). "It is suggested that PRMT5 performs a very important function on the cell migration in pancreatic cancer cells." (PMID 31851779, 2020). "In this study, we confirm that PRMT5 is overexpressed in human pancreatic cancer at both mRNA and protein levels, and acts as an independent prognostic factor for patient outcome." (PMID 31851779, 2020). "It is further suggested that PRMT5 plays an important role in cell proliferation of pancreatic cancer cells." (PMID 31851779, 2020). "In summary, our study provides proof that PRMT5 promotes EMT in pancreatic cancer cells probably through activating EGFR/AKT/β‐catenin signalling." (PMID 31851779, 2020). "We found that PRMT5 mRNA level was higher in pancreatic cancer tissues than that in normal pancreatic tissues (1.03 ± 0.48 vs 1.60 ± 0.39, P < .001, n = 78) in Badea pancreas database." (PMID 31851779, 2020). "To investigate the effects of PRMT5 on cell growth in pancreatic cancer cells, we first used the CCK8 assay to determine the growth curves and then evaluated their ability of colony formation." (PMID 31851779, 2020). "By Kaplan–Meier analysis on pancreatic cancer, the level of each gene is linked to survival probability, with high expression for E2F1, PRMT5 and cortactin/CTTN linked to poor survival." (PMID 32709847, 2020). "More importantly, we confirm that PRMT5 promotes EMT through EGFR/AKT/β‐catenin pathway in pancreatic cancer cells." (PMID 31851779, 2020). "All these findings suggest that PRMT5 is a potential biomarker for diagnostics and prognosis of pancreas cancer." (PMID 31851779, 2020). "In summary, the present study revealed PRMT5 as a novel prognostic marker for overall survival in pancreatic cancer." (PMID 30922330, 2019). "Subsequently, we investigated the ability of PRMT5 expression to predict overall survival in patients with pancreatic cancer." (PMID 30922330, 2019). "In the present study, our results demonstrated that PRMT5 was an unfavorable prognostic factor for pancreatic cancer." (PMID 30922330, 2019). "Clinically, elevated expression of PRMT5 was positively correlated with worse overall survival in pancreatic cancer patients." (PMID 30922330, 2019). "Silencing PRMT5 expression inhibited the proliferation of pancreatic cancer cells both in vitro and in vivo." (PMID 30922330, 2019). "First, we examined the expression status of PRMT5 in pancreatic cancer cell lines, including HPDE, Capan-1, PANC-1, BxPC-3, MIA PaCa-2 and SW1990." (PMID 30922330, 2019). "Real-time PCR, immunohistochemistry and analysis of a dataset from The Cancer Genome Atlas (TCGA) were performed to study the expression of PRMT5 at the mRNA and protein levels in pancreatic cancer." (PMID 30922330, 2019). "PRMT5 expression was significantly upregulated in pancreatic cancer tissues compared with that in adjacent normal tissues." (PMID 30922330, 2019). "Our studies are the first to identify the important roles of PRMT5 in predicting overall survival and promoting tumorigenesis in pancreatic cancer." (PMID 30922330, 2019). "In conclusion, we first reported that increased expression of PRMT5 is an unfavorable prognostic marker in pancreatic cancer." (PMID 30922330, 2019).